CD34 (CD34 molecule)
Diseases named in the same sentence as CD34 in open-access papers (continued):
Sharing a sentence is not in itself a finding about the gene and the disease.
lung cancer (continued). "Recently, hematopoietic stem cells (identified as CD133+CD34+CD45+ cells) were also found in the peripheral blood of patients with lung cancer, and their number negatively correlated with time to progression." (PMID 23959111, 2014). "In peripheral lung cancers, positive staining of CD34 were found in the tissues of small artery, small vein, capillary and blood vessel endothelium of lung cancer tissues, which were stained brown." (PMID 18590539, 2008). "Further work is in progress in our laboratory to test the possibility of using fascin as a more suitable marker of neoangiogenesis than CD34 in lung cancers." (PMID 12592367, 2003). "To address these questions we therefore analyzed parallel samples of tumor tissue, uninvolved lung tissue and PBMC from 5 patients undergoing surgery for lung cancer CD34+DNAM-1brightCXCR4+ cells could be identified, in addition to PBMC, in all tissue samples." (PMID 38390333, 2024). "In addition, due to the high expression of neovascularization EC markers CD31, CD34, and CD105, the presence and abnormal morphology of penetrating vessels are pathological risk factors for the occurrence and development of lung cancer." (PMID 36185269, 2022). "Moreover, miR-32*, miR-466i-5p, and mmu-miR-669c in SP+ lung cancer stem cells were confirmed, as well as mmu-miR-106b*, mmu-miR-144, mmu-miR-669k*, mmu-miR-142-3p, mmu-miR-210, and mmu-miR-223 in CD34+SCA1+ bone marrow hematopoietic stem cells." (PMID 28977934, 2017). "Elevated serum VEGF-A levels and upregulated expression of VEGF-A, CD34 and CD31 markers in tumor tissues confirm the ability of A. fumigatus to promote angiogenesis in lung cancer." (PMID 41249582, 2025). "While comparatively analyzed tumor microvascular density (MVD) (CD34 staining), a notable difference in MVD was found between the primary lung cancers and paired BMs, and inter-BMs, with tumor MVD more plentiful in BMs than in the paired primary tumors." (PMID 37384291, 2023). "Some studies have also analyzed additional markers obtained by CD34 and/or CD31 staining for BV analysis in samples of lung cancer and colorectal cancer." (PMID 38323039, 2023). "The expression of CD31, CD34, and CD105 in different lung tissues was significantly different, with remarkably higher iMVD in lung cancer tissues than in adjacent normal lung tissues." (PMID 36185269, 2022). "y Expression of CD31-, CD34-, and CD105-labeled iMVD in lung cancer tissues, paracancer normal lung tissues, and proglandular lesions." (PMID 36185269, 2022). "The relationship between iMVD of lung cancer tissue marked by CD31, CD34, and CD105 and clinicopathological parameters of patients." (PMID 36185269, 2022). "The expression of CD31-, CD34-, and CD105-labeled lung cancer tissue iMVD was significantly different among patients with a different smoking history (p < 0.05), tumor diameter (p < 0.05), and surgical procedure (p < 0.05)." (PMID 36185269, 2022). "The expression status of CD31, CD34, and CD105 was closely related to tissue type, and their expression status was significantly different between lung cancer tissues, precursor glandular lesion tissues, and normal lung tissues adjacent to tumor." (PMID 36185269, 2022). "To investigate the prognostic and clinical impact, we analyzed CD34+ and SMA+ CAFs in non‐small cell lung cancer (NSCLC)." (PMID 31760702, 2020). "The expression profiles of five stem cell markers (CD34, CD44, CD133, BMI1 and OCT4) were screened by flow cytometry in 10 lung cancer cell lines." (PMID 21124918, 2010). "To explore further lung CSC markers, we have screened the expression profile of CD34, CD44, CD133, BMI1 and OCT4 in 10 lung cancer cell lines by flow cytometry." (PMID 21124918, 2010). "We analyzed the expression profile of putative surface (CD34, CD44, CD133) and nuclear markers (BMI1, OCT4) of stem cells in 10 lung cancer cell lines using flow cytometry." (PMID 21124918, 2010).
lung cancer (continued). "In addition, A. fumigatus spore inhalation elevated CD34 and CD31, upregulated Vegf-a gene levels, and increased VEGF-A in tumors and serum in orthotopic lung cancer models." (PMID 41249582, 2025). "Previous studies on the correlation between CD34-MVD and lung cancer have yielded mixed results, which may have been due to the following reasons." (PMID 39906069, 2025). "In lung cancer studies, the expression of CD31, CD34, and CD105 was found to be closely related to the type of tissue, differing significantly between cancerous tissues, pre-cancerous tissues, and healthy tissues adjacent to tumors, indicating their potential as indicators of tumor malignancy." (PMID 39399171, 2024). "The fact that mast cells may promote tumor angiogenesis is supported by the positive correlation between MCD and CD34-MVD, which aligns with findings in other studies on mast cells and angiogenesis in lung cancer." (PMID 38834833, 2024). "CD105 could be expressed weaker in lung cancer tissues than CD31 and CD34, with a lighter brownish-yellow color and unclear boundary with the background." (PMID 36185269, 2022). "Furthermore, we analyzed the correlation of the expression of hub gene in lung cancer tissues, of which PECAM1, VWF, CD34, COL1A1, MMP9 and TIMP1 are closely related." (PMID 33850663, 2021). "In flowcytometry analysis, CD34 and CD45 were expressed extremely low in these lung cancer cell lines (data not shown), while the chemokine receptor CXCR4 was highly expressed in the HTB-182 cell line, but not expressed in the remaining cell lines." (PMID 23738757, 2013).
atherosclerosis (43 papers, 2009 to 2025). A disease characterized by the build-up of fatty material and calcium deposition in the arterial wall resulting in partial or complete occlusion of the arterial lumen. "Previously, LDLc was revealed to be positively associated with structural atherosclerosis and inversely associated with functional atherosclerosis, possibly by stimulating the proliferation of CD34-positive cells." (PMID 37099591, 2023). "Development of structural atherosclerosis, an established cardiovascular risk factor, requires hematopoietic stem cells known as CD34-positive cells." (PMID 36528703, 2022). "Because of aggressive endothelial repair that causes atherosclerosis progression, several CD34+ cells were differentiated into mature cells, such as endothelial, mural, and foam cells." (PMID 32170211, 2020). "In the present study, our results indicate a significant positive association between γ-GTP and atherosclerosis in participants with high CD34-positive cell levels." (PMID 31785607, 2019). "Second, a positive association between γ-GTP and atherosclerosis should be limited to subjects with a higher number of CD34-positive cells and consequently have a higher capacity of endothelium maintenance." (PMID 31785607, 2019). "Investigations of the associations between γ-GTP and the two CD34-positive cell groups (high level and low level) on atherosclerosis revealed a significant interaction." (PMID 31785607, 2019). "SDF-1/CXCR4 biological axis consisting of SDF-1 and its receptor CXCR4 induced CD34+ stem cells to differentiate into macrophages and foam cells, which later caused the atherosclerosis." (PMID 26074989, 2015). "CD34+ cell number appeared to be associated with vitamin D levels, and negatively correlated to fibrinogen and early atherosclerosis markers (PWV and cIMT); vitamin D levels appear also to be inversely associated to fibrinogen." (PMID 26241902, 2015). "CD34+ CD45dim Lineage- hematopoietic stem/progenitor cells (HSPCs) give rise to the inflammatory cells linked to atherosclerosis." (PMID 23991206, 2013). "Alzheimer's disease (AD) and atherosclerosis share common vascular riskfactors such as arterial hypertension and hypercholesterolemia.Adipocytokines and CD34+ progenitor cells are associatedwith the progression and prognosis of atherosclerotic diseases." (PMID 21633502, 2011). "In our study, we found, after adjusting for 10-year CVD risk, a significant and inverse association between CD34+ cells and measures of subclinical atherosclerosis that are strong predictors of CVD risk." (PMID 20407620, 2009). "Because of the association between BMI and ln(CD34+), the strength of the associations between ln(CD34+) and the subclinical measures of atherosclerosis were attenuated." (PMID 20407620, 2009). "To further explore the significant association between CD34+ cell counts and measures of subclinical atherosclerosis in the current study, we stratified the study group into men with 10-year CVD risk <10% and men with 10-year CVD risk ≥10%." (PMID 20407620, 2009). "The level of circulating CD34-positive endothelial progenitor cells (EPCs) may provide clinical information about the extent of atherosclerosis and future cardiovascular risk." (PMID 40650017, 2025). "In addition, because shortages of CD34-positive cells lead to the progression of functional atherosclerosis, circulating CD34-positive cell count was inversely associated with CAVI only among participants with low circulating CD34-positive cell counts." (PMID 37511963, 2023). "In addition, a significant association between γ-GTP and structural atherosclerosis was observed in participants with high CD34-positive cell count (at or above the median)." (PMID 36528703, 2022). "In people with structural atherosclerosis, functional atherosclerosis may develop both due to aggressive endothelial repair and to insufficient endothelial repair caused by a shortage of CD34-positive cells due to consumption." (PMID 36615839, 2022).
atherosclerosis (continued). "Furthermore, due to consumption, aggressive vascular repair that relates to the development of structural atherosclerosis, also causes a reduction in circulating CD34-positive cell count." (PMID 35887757, 2022). "Despite this, aggressive endothelial repair (progressing atherosclerosis) might cause a wasting reduction in CD34+ cells, which could result in a lower capacity of endothelial repair and hypertension." (PMID 32170211, 2020). "We therefore speculate that vascular maintenance provided by circulating CD34-positive cells is one possible background mechanism behind the positive association between handgrip strength and carotid subclinical atherosclerosis." (PMID 29050209, 2017). "Further investigations of associations of CD34+ cell count with subclinical atherosclerosis in asymptomatic individuals could provide mechanistic insights into the atherosclerotic process." (PMID 20407620, 2009). "As the presence of baseline atherosclerosis could cause a shortage of circulating CD34-positive cells due to heavy consumption, as in our previous study, a significant inverse association between baseline atherosclerosis and active arterial wall thickening was observed." (PMID 36552266, 2022). "In addition, the aggressive endothelial repair that causes atherosclerosis might induce a wasting reduction of circulating CD34+ cells which result in a shortage of the mediators of endothelial repair." (PMID 32170211, 2020). "Moreover, hypertension, which is positively associated with baseline subclinical atherosclerosis, could also be associated with the wasting reduction of circulating CD34+ cells." (PMID 32170211, 2020). "However, although both platelet and CD34-positive cell production are stimulated by endothelial injury, aggressive endothelial repair (the cause of atherosclerosis) may cause consumptive reduction of CD34-positive cells, but not platelets." (PMID 29487687, 2018). "For instance, in transplant atherosclerosis models, host-derived CD34+ lineage cells differentiate into Tfh cells through mitochondrial one-carbon metabolism." (PMID 41562048, 2025). "These include CD34+ cell differentiation into Tfh cells via mitochondrial one-carbon metabolism driving transplant atherosclerosis, and the synergistic role of immunoproteasome subunits in chronic rejection." (PMID 41562048, 2025). "For example, in transplant atherosclerosis models, CD34+ lineage cells differentiate into Tfh cells via this pathway, promoting tertiary lymphoid structure formation and vascular remodeling." (PMID 41562048, 2025). "The depletion of CD34+ cells leads to endothelial repairdefects, which further exacerbates functional atherosclerosis instead ofstructural atherosclerosis." (PMID 39077331, 2024). "In conjunction with hematopoietic stem cells known as CD34-positive cells, platelets play an important role in endothelial repair, including the development of atherosclerosis." (PMID 39621597, 2024). "Circulating CD34-positive cells, which play a major role in endothelial repair, are necessary for the development of structural atherosclerosis." (PMID 37511963, 2023). "Sufficient numbers of CD34-positive cells are mandatory for the development of structural atherosclerosis." (PMID 37511963, 2023). "Structural atherosclerosis requires CD34-positive cells, which contribute to endothelial repair, while a shortage of CD34-positive cells results in functional atherosclerosis but not structural atherosclerosis." (PMID 36615839, 2022). "CD34-positive cells are known contributors to atherosclerosis; they have been reported to differentiate into macrophages and foam cells." (PMID 35159980, 2022). "CD34-positive cells contribute to both maintenance of the microcirculation and development of structural atherosclerosis." (PMID 36528703, 2022). "Consistently, CD34+KDR+ cell count correlates with cumulative indexes of CV risk and is an independent predictor of atherosclerosis progression and CV events." (PMID 35923624, 2022).
atherosclerosis (continued). "In conjunction with activated platelets, CD34-positive cells play an important role in endothelial repair, including furthering the progression of structural atherosclerosis." (PMID 36615839, 2022). "In this study, we aimed to evaluate the effects of PCSK9-i on CD34+CPCs and on early atherosclerosis damage, evaluated by pulse wave velocity (PWV) in a cohort of FH subjects." (PMID 35885020, 2022). "This study about circulating CD34-positive cells describes a novel mechanism that explains the beneficial effect of hypertension and the development of structural atherosclerosis." (PMID 36528703, 2022). "Since aging is a process that decreases the production of CD34-positive cells, development of structural atherosclerosis partly indicates residual capacity to maintain the microcirculation." (PMID 36528703, 2022). "Circulating CD34-positive cells, which play an important role in endothelial repair, coordinate the beneficial effect of hypertension and structural atherosclerosis on vascular health." (PMID 36528703, 2022). "The effect of circulating CD34-positive cell count (low or high) on the association between γ-GTP and structural atherosclerosis was evaluated." (PMID 36528703, 2022). "With participants in the lowest γ-GTP quartile (Q1) as the referent group, the fully adjusted OR and 95% CI of structural atherosclerosis for high CD34-positive cell count was 1.52 (0.46, 4.97) for Q2, 1.77 (0.58, 5.41) for Q3, and 4.28 (1.34, 13.63) for Q4." (PMID 36528703, 2022). "Aggressive endothelial repair, which is related to the development of structural atherosclerosis, also decreases the number of circulating CD34-positive cells due to consumption." (PMID 36615839, 2022). "Since macrophages and foam cells contribute to the development of pathological atherosclerosis, CD34-positive cells are necessary for the development of structural atherosclerosis." (PMID 35887757, 2022). "Previous studies described a bimodal action of circulating CD34+ cell number in atherosclerosis development." (PMID 35885020, 2022). "Circulating CD34-positive cells are necessary to activate endothelial repair, while atherosclerosis is the result of aggressive endothelial repair." (PMID 33549053, 2021). "Since bone marrow-derived hematopoietic stem cells (CD34-positive cells) contribute to endothelial repair, bone marrow activity is crucial for the progression of atherosclerosis." (PMID 33549053, 2021). "In other words, among participants with high levels of circulating CD34-positive cells, the presence of atherosclerosis also indicates the presence of angiogenesis, which reduces the risk of hypertension by decreasing oxidative stress." (PMID 33549053, 2021). "Age-related physical changes, such as low-grade inflammation and increased oxidative stress, induce endothelial repair and cause active arterial wall thickening by stimulating the production of CD34+ cells (the principal mediators of atherosclerosis)." (PMID 32170211, 2020). "This previous study also supports the theory that higher numbers of circulating CD34+ cells indicates that there is enough material for atherosclerosis to develop (active arterial wall thickening)." (PMID 32170211, 2020). "Among participants with high CD34-positive cells, γ-GTP showed significant and positive association with atherosclerosis (OR of the log-transformed value of γ-GTP (OR) = 2.26 (1.32, 3.86)) but not with hypertension (OR = 0.77 (0.51, 1.17))." (PMID 31785607, 2019). "CD34+ circulating progenitor cells (CD34+CPCs) are a population of multipotent cells which can delay the development of atherosclerosis and cardiovascular disease (CVD) in conditions of increased CV risk." (PMID 28301500, 2017). "Platelets and circulating CD34-positive cells have been reported to contribute to vascular repair (endothelial repair and developing atherosclerosis)." (PMID 27374094, 2016).